STAT2 (signal transducer and activator of transcription 2)
Diseases named in the same sentence as STAT2 in open-access papers (continued):
Sharing a sentence is not in itself a finding about the gene and the disease.
tumor (110 papers, 2009 to 2026). "Removing the receptor for type I IFN caused tumor cells to grow rapidly, showing that STAT2 can drive tumor growth independently of this pathway." (PMID 41440237, 2025). "The expression of STAT2 was almost negatively associated with all tumor types except ACC, SKCM, and PCPG." (PMID 36176415, 2022). "We demonstrated that high CXCL10/STAT2 expression was associated with activation of T-cell pathways, increased tumor infiltration of Th1 and CD8+ T cells, and better patient outcome." (PMID 35207629, 2022). "This study also demonstrates that high CXCL10/STAT2 expression (HH subgroup) is associated with activation of T-cell pathways, increased tumor infiltration of Th1 and CD8+ T cells, and good patient prognosis." (PMID 35207629, 2022). "The location of the most recurrent STAT2 mutations in our cohort in the C-terminal transactivation domain might indicate a loss of function, which is interesting in the tumor-suppressing context described for STAT2." (PMID 40234614, 2025). "Moreover, the tumor-promoting role of STAT2 identified here aligns with emerging evidence in other diseases, where STAT2 has been implicated in sustaining chronic inflammation." (PMID 41440237, 2025). "This analysis identified a motif for STAT1:STAT2 as the most highly enriched motif, providing evidence that the down-regulation of the mRNAs encoding STAT1 and STAT2 is functionally related to genes exhibiting reduced expression in the Ly6C monocytes of tumor-bearing mice." (PMID 35159100, 2022). "The interaction of STAT2 and PD-L1 might be associated with tumour immune evasion in cancers, suggesting the potential value for tumour treatment." (PMID 35946310, 2022). "While STAT3/STAT5 are established oncogenes and STAT1/STAT2 are classically viewed as tumor suppressors, emerging evidence indicates context-dependent roles in tumorigenesis." (PMID 42195004, 2026). "Co-expression analysis highlights genes like PIK3R5 (PI3K–AKT signaling), CEBPB (linking inflammation to tumor progression), and STAT2 (JAK–STAT amplification)." (PMID 41303731, 2025). "To assess the functional impact of Stat2 and Ifnar1 deletion on tumor cell growth, we evaluated their proliferative capacity in vitro and in vivo." (PMID 41440237, 2025). "Functionally, our study shows that loss of STAT2 suppressed tumor cell proliferation and impaired tumor growth in vivo, whereas loss of IFNAR1 produced the opposite effect, resulting in enhanced tumor growth." (PMID 41440237, 2025). "In this study, we report a mechanism by which the ubiquitination of STAT2 in IFN-treated tumor cells leads to its secretion instead of degradation, ultimately promoting enhanced immune activation." (PMID 41321309, 2025). "In preclinical models, deletion of STAT2 in tumor cells suppressed tumor growth, whereas STAT2 overexpression enhanced tumor growth, supporting its pro-tumorigenic role." (PMID 41440237, 2025). "Removing STAT2 from tumor cells slowed tumor growth, while increasing STAT2 made tumors grow faster." (PMID 41440237, 2025). "Elevated STAT2 expression has been associated with poor prognosis in several cancers, and experimental evidence indicates that STAT2 can support tumor cell survival and chemoresistance through both canonical and non-canonical signaling mechanisms." (PMID 41440237, 2025). "To assess the impact of STAT2 and IFNAR1 loss on tumorigenicity, we implanted each cell line subcutaneously into immunodeficient Rag1 KO mice and monitored tumor growth over time." (PMID 41440237, 2025). "In further spatial localization analysis, we observed that there is an increased expression of STAT2 and PD‐L1 in tumor tissues overexpressing Nfkb2 as well as in CRC samples with high NFKB2 expression." (PMID 38660687, 2024). "Positive associations of several TF-encoding genes such as ZNF683 (HOBIT), STAT2, and IRF3 with the abundances of tumour-infiltrating CD56bright NK and CD8+ TEM cells were observed." (PMID 39877370, 2024).
tumor (continued). "Overexpression of IRF9 or STAT2 slowed BRAFis-induced tumor shrinkage, while knockdown of IRF9 or STAT2 accelerated BRAFis-induced tumor shrinkage." (PMID 39802949, 2024). "Signal transducer and activator of transcription 2 (STAT2), a member of the STAT transcription factor family, is implicated in regulating tumor development." (PMID 39600540, 2024). "It was shown that STAT3 and STAT5 are involved in tumor initiation and progression, while STAT1 and STAT2 play an essential role in anti-tumor defense and long-term immune response." (PMID 39136000, 2024). "The use of recently produced Stat2-conditional knockout mice will be instrumental in addressing the precise nature of STAT2-dependent signals in tumor cells and the tumor microenvironment." (PMID 38001683, 2023). "Histologic analysis of colon sections revealed the higher penetrance of tumors in the ApcMin/+ WT mice compared with the ApcMin/+ Stat2−/− mice (T indicates tumor)." (PMID 38001683, 2023). "In vitro studies using various cell lines indicated that STAT2 mediates the anti-tumor effects of type I IFN." (PMID 38001683, 2023). "The mechanistic details by which STAT2 controls the initiation (reflected by the tumor number) and the progression (reflected by tumor size) phases of tumorigenesis remain to be addressed by future studies." (PMID 38001683, 2023). "Consistent with activation of the type I IFN pathway, we found that MUC1 significantly associates with (i) STAT2 and IRF9 expression in TNBC tumors and (ii) IRF9 in a scRNA-seq dataset from TNBC tumor cells." (PMID 35681561, 2022). "Despite the increasing number of studies examining STAT2, the effects of STAT2 in anti-tumour immunity remain controversial." (PMID 35946310, 2022). "IRF9 and unphosphorylated STAT2 cooperate with NF-kB to induce IL-6 expression, a cytokine that promotes tumour growth of EGFR-driven GBM in an autocrine and paracrine manner." (PMID 36010867, 2022). "The genes upregulated in MΦ subtypes from tumours treated with topical caerin gel including Stat2, Isg15, Tap1, Psmb9, and Parp9, were more highly expressed in the CCI than CCII MΦs." (PMID 36497272, 2022). "Jak-STAT signaling pathway inhibition is involved in anti-tumor activity in several pre-clinical studies and continued activation of STAT1 and STAT2,which are essential components of JAK/STAT pathway, are associated with suppressing tumor apoptosis." (PMID 35392800, 2022). "Our study identified STAT2 as a direct upstream TF that regulates PD-L1 expression, suggesting its potential to be used as a therapeutic target for tumour treatment." (PMID 35946310, 2022). "In a renal cell adenocarcinoma study, IRF9 knockdown was shown to increase tumor formation in a xenograft model, whereas the overexpression of both IRF9 and STAT2 reduced tumor growth." (PMID 33430083, 2021). "In another study, STAT2 knockout mice formed larger tumors than wild-type mice, indicating that STAT2 reduces tumor growth in a syngeneic tumor transplantation model." (PMID 33391406, 2021). "We have observed significant upregulation of IFNG, JAK3, STAT1, and STAT2 in tumor compared to normal samples." (PMID 33980865, 2021). "The JAK-STAT signaling pathway is a double-edged sword in CIT, and both STAT1 and STAT2 drive anti-tumor immune responses by inducing type I and type II interferon (IFN)." (PMID 34852825, 2021). "STAT1 and STAT2 are important components of the JAK/STAT pathway, and continued activation of the JAK/STAT signal is associated with tumor progression." (PMID 32685473, 2020). "While the contribution of STAT2 for T cell-mediated tumor surveillance has been unequivocally documented, the role of STAT2 in NK cell-mediated tumor surveillance is still enigmatic." (PMID 31781102, 2019). "In many cases the protein expression levels of PBRM1, SETD2 or BAP1 correlated with that of STAT2 or IRF9 on the same tumor samples." (PMID 30355451, 2018).
tumor (continued). "Adenocarcinoma had lower IRF7 levels in the tumor tissue (p value 0.001) and higher STAT2 expressions in the normal tissue (p value 0.001) than SCC." (PMID 30305853, 2018). "The protein level of IRF7 was correlated only with that of STAT2 in the tumor tissue but with those of molecules other than STAT2 and IFNAR1 in the normal tissue." (PMID 30305853, 2018). "For example, when the pooled tumor samples were compared against pooled normal samples, only two TFs (Stat1 and Stat2) were identified." (PMID 23885756, 2013). "Our results indicate Stat1 and Stat2 show differential activities between tumor and normal breast epithelium samples." (PMID 23885756, 2013). "Our results indicate that Stat1 and Stat2 are significantly more active (i.e. their target genes tend to be more highly expressed) in tumor cells than normal cells." (PMID 23885756, 2013). "Finally, our findings were further validated by demonstrating that LINC00543 regulated the tumour immune microenvironment in CRC by downregulating STAT1/STAT2 expression." (PMID 39868645, 2025). "However, in xenograft tumor transplantation models, IFNAR1 KO cells formed larger tumors while STAT2 KO tumor cells formed smaller ones compared to parental tumor cells." (PMID 41440237, 2025). "Recent studies from our group and others have reported that STAT2 may paradoxically promote tumor progression under specific conditions." (PMID 41440237, 2025). "IP of IRF9 in THP1-MΦ coprecipitated the FLAG-tagged STAT2 derived from tumor cells." (PMID 41321309, 2025). "In contrast, STAT1 and STAT2 often play tumor-suppressive and immunoprotective roles." (PMID 41438753, 2025). "Specifically, the activation of the STAT1 pathway induces M1 polarization of macrophages, exerting inflammatory functions and cytotoxic effects, whereas the activation of the STAT2 pathway mediates M2 polarization of macrophages, inhibiting tumor immunity and promoting the progression of GC." (PMID 40858547, 2025). "STAT2 plays a critical role in the host STAT2/type I interferon axis, which controls tumor growth." (PMID 40842996, 2025). "While IFNAR1 loss did not accelerate tumor growth, STAT2 deletion consistently suppressed cell proliferation and tumor formation in both human and murine models." (PMID 41440237, 2025). "In vitro, IFNAR1 KO and STAT2 KO tumor cells proliferated at similar rates." (PMID 41440237, 2025). "STAT2 is a key regulator of the STAT2/type I interferon axis, which governs tumor progression." (PMID 40842996, 2025). "Furthermore, decreased levels of STAT2 hampered the anti-tumor immune response in luminal BC by affecting the activation of type I IFN signaling upon inhibition of EZH2." (PMID 40707929, 2025). "Studies have shown that Stat2, as a member of the Stat family, plays a crucial role in immune responses to both extracellular and intracellular stimuli, including cancer initiation, inflammatory responses, and tumor cell invasion." (PMID 39840059, 2024). "TCGA analysis revealed that STAT2 was up-regulated in tumor groups." (PMID 39600540, 2024). "It found that tumor-associated macrophages had upregulated genes regulated by IRF2, IRF7, IRF9, and STAT2, and downregulated genes regulated by Fos/Jun and IRF8, revealing decreased inflammatory response, TNF-α-induced proliferation, and reactive oxygen species production pathways." (PMID 39034998, 2024). "Accumulating evidence suggests that STAT2 may be a critical player in the tumor microenvironment as it was shown to be able to either promote or block tumorigenesis." (PMID 38001683, 2023). "Notably, in non-tumor tissue samples, the levels of pSTAT3 and STAT3 were lower in WT as compared with Stat2-deficient ApcMin/+ mice." (PMID 38001683, 2023). "STAT2 promotes tumor immune escape by upregulating PD-L1 expression." (PMID 37600786, 2023). "The JAK/STAT pathway involved by STAT2 can affect the tumor immune microenvironment." (PMID 37600786, 2023).
tumor (continued). "Transcription factor (TF) activity prediction, using the DoRothEA resource, to identify potential regulons responsible for the signalling and phenotypes associated with HPS in HiFi tumours revealed a strong association with STAT1, STAT2, IFN (IRF1, IRF9) and NFκB (NFKB1, REL, RELA, RELB) TFs." (PMID 35477539, 2022). "Moreover, STAT1 and STAT2, which were defined as ccRCC tumor activated TFs, were also significantly upregulated in GP1 (p < 0.05)." (PMID 35440542, 2022). "In addition to detecting gene expression, we found that GINS2 knockdown increased STAT1 and STAT2 protein expression and inhibited tumor migration and proliferation, which was consistent with a previous study." (PMID 33391406, 2021). "However, there are very few studies in this regard, and more research must be generated to determine if the activation of the STAT6 homodimer or the STAT6/STAT2 heterodimers can contribute to the process of tumor recognition and elimination." (PMID 33076315, 2020). "While STAT2 and STAT4 promote the anti-tumor immune response, STAT3 and STAT6 mediate immunosuppression in the TME, and STAT1 and STAT5 have been implicated in both activation and suppression of the anti-tumor immune response." (PMID 31057536, 2019). "Therefore, we propose balancing pro-tumor STAT3 activation with anti-tumor STAT1/STAT2 activation as a novel therapeutic approach." (PMID 31684144, 2019). "To study the effects of pardaxin on tumor functions, we performed a real-time RT-PCR analysis of caspase-3, caspase-7, caspase-8, caspase-9, Bax, Bcl-2, STAT2, ATF3, STAT3, SOCS3, IL-2, cathelicidin, TNF-α, MyD88, NF-κB1, p65, IFN-β1, IFN-γ, IL-1β, IL-6, IL-7r, and IL-10." (PMID 23015777, 2012). "However, recent studies, including ours, find that STAT2 can promote tumor growth." (PMID 41440237, 2025). "Future experiments, such as performing a ChIP assay for STAT2 to identify target genes with tumorigenic function and using mutants of STAT2 that cannot be tyrosine phosphorylated, will provide initial mechanistic insight into how STAT2 may promote tumor growth." (PMID 41440237, 2025). "However, emerging evidence suggests that STAT2 can also promote tumor growth." (PMID 41440237, 2025). "We then tested whether STAT2’s tumor-promoting effects depended on the type I IFN pathway." (PMID 41440237, 2025). "We further evaluated whether STAT2’s tumor-promoting activity depends on canonical IFN-I signaling." (PMID 41440237, 2025). "Notably, high STAT2 expression has been reported to be associated with reduced survival in other types of cancer, which has prompted further investigation, and recent studies support the notion that STAT2 may act as a tumor promoter." (PMID 41440237, 2025). "Similarly, KIRC patients exhibited a significant upregulation in the expression of STAT2 protein compared to the normal healthy persons in the sub-group analyses based on sample types, race, gender, age, weight, tumor grade, cancer stages, and nodal metastasis status." (PMID 37115061, 2023). "Using two independent mouse models relying on different pathogenetic mechanisms coupled with functional experiments in tumoroids, we could show that STAT2 promotes CRC and is implicated in the resistance of tumor cells to the anti-cancer agents 5-Fluorouracil and Cisplatin." (PMID 38001683, 2023). "Some studies have shown that STAT2 may be a tumor suppressor by acting downstream of IFN-I." (PMID 34276757, 2021). "However, IFN-α possesses anti-tumor activity and some evidence suggests that STAT2 might be of relevance concerning cancer development." (PMID 26938566, 2016). "Moreover, activating mutations of KRAS as they occur in colon cancer downregulate STAT2 expression, which might contribute to the reduced sensitivity of tumor cells to interferons." (PMID 26938566, 2016). "Single-cell analysis demonstrated tumor-cell-autonomous upregulation of STAT1 and STAT2 in the HNSCC dataset." (PMID 42195004, 2026).
tumor (continued). "Aberrant STAT1 and STAT2 phosphorylation can be activated by IFN signalling, executing the antitumor effects of IFNs and contributing to tumour immune responses." (PMID 39868645, 2025). "We then assessed the expressions of GLDC and ISGF3 in xenografted tumor tissues and confirmed decreased GLDC and increased IRF9 and STAT2 expressions." (PMID 39781465, 2025). "STAT2 deficiency in NPC cells abolished the increase in p-STAT1 and p-STAT2 in cocultured THP1-MΦ, implying the transfer of p-STATs from tumor cells to macrophages." (PMID 41321309, 2025). "Analysis of basal protein levels revealed that total expression of STAT1, STAT2, and STAT3 remained largely unaffected in both STAT2 KO and IFNAR1 KO tumor cells, indicating that deletion of either gene does not alter steady-state STAT2 protein abundance." (PMID 41440237, 2025). "Meanwhile, STAT2, a key molecule in the JAK-STAT signaling pathway, also showed upregulation in Il1r2−/− tumor cells." (PMID 40767963, 2025). "circCAPRIN1 interacts with signal transducer and activator of transcription 2 (STAT2) to increase the expression of ACC1 and promote tumor progression and lipid synthesis of CRC cells." (PMID 39103344, 2024). "In CC cases with heterogeneous EMR1 expression, specific JAK-STAT genes (JAK2, JAK3, STAT1, STAT2, and STAT3) were upregulated in the EMR1-H/L ROI compared to those in the EMR1-N ROI within the same tumor." (PMID 38673975, 2024). "Activation of STAT1, STAT2, STAT3, STAT4, and STAT6 was observed in expanded bile duct epithelium and tumor cells, while expression of STAT5a and STAT5b was found in macrophages and connective tissues surrounding the tumor." (PMID 39290697, 2024). "STAT2 is a mediator in the signaling pathway of type I interferons (IFN-α and IFN-β) that is involved in immune reactions regulating tumor cells’ capability to escape, survive and progress." (PMID 39273294, 2024). "Next, we detected numerous lymphocyte development and function associated pathways that are significantly associated with ZNF683 (HOBIT), STAT2, and IRF3 expression, indicating that these TFs may regulate the priming, and their downstream functionalities of tumour-infiltrating NK and CD8+ T cells." (PMID 39877370, 2024). "In the immune exclusion tumour area, STAT1 and STAT2 from the STAT family showed increased regulon activities, which contribute to the promotion of proliferation, survival, angiogenesis and immunological escape." (PMID 39187937, 2024). "Our data indicate that tumor cells reshape and evade STING-mediated antitumor effects by manipulating the expression level and T404 phosphorylation of STAT2." (PMID 37036972, 2023). "IFN-λ acts in conjunction with related genes such as STAT1, STAT2, and STAT3 to affect the JAK-STAT signaling pathway, which promotes tumor progression." (PMID 37697300, 2023). "Taken together, it was implied that up-regulation of STAT2, STAT4, and STAT5B meant down-regulation of HNSC tumor stemness characteristics." (PMID 36968603, 2023). "In general, it was displayed that higher expression of STAT1, STAT2, STAT3, STAT4, and STAT5A indicated a lower tumor purity." (PMID 36968603, 2023). "Taken together, we concluded that a tumor sample with high STAT1, STAT2, STAT4, and STAT5B expression levels tended to be enriched in T cell dysfunction phenotypes, while STAT6 showed to be the opposite." (PMID 36968603, 2023). "STAT2 was detected in KIRC patients thereby revealing that it was up-regulated at both the mRNA and protein levels in tumor tissues." (PMID 37115061, 2023). "On the whole, it was illustrated that higher the expression of STAT1, STAT2, STAT3, STAT4, STAT5A, and STAT5B, the lower the tumor purity." (PMID 36968603, 2023). "In the greatest number of tumors, STAT4 was correlated with tumor growth, then STAT1, STAT3, STAT6, STAT5B, STAT2, and STAT5A." (PMID 36176415, 2022).